HSPB1 (heat shock protein family B (small) member 1)
Diseases named in the same sentence as HSPB1 in open-access papers (continued):
Sharing a sentence is not in itself a finding about the gene and the disease.
ovarian carcinoma (4 papers, 2020 to 2025). A malignant neoplasm originating from the surface ovarian epithelium. "More recently, high serum HspB1 expression in ovarian cancer and renal cancer has been shown to be associated with tumor metastasis." (PMID 32927696, 2020). "In summary, these data establish HSPB1 as an effector of ZKSCAN3 that promotes ovarian cancer cell proliferation." (PMID 41393507, 2025). "We find that HSPB1 is required for the regulation of cell proliferation by ZKSCAN3 in ovarian cancer cells." (PMID 41393507, 2025). "HSPB1 also affects ovarian cancer response to therapy and serves as an independent prognostic factor." (PMID 41393507, 2025). "Both cell counting and colony formation assays showed that HSPB1 knockdown significantly inhibited proliferation in ovarian cancer cells." (PMID 41393507, 2025). "Western blot showed ZKSCAN3-KD indeed decreased the HSPB1 protein level in three different ovarian cancer cell lines, which was consistent with the change in mRNA level." (PMID 41393507, 2025). "For example, HspB1 mRNA and protein expression correlate with peritoneal metastasis and poor survival in ovarian cancer." (PMID 32927696, 2020). "In addition, we find that the regulation of HSPB1 contributes to ZKSCAN3 function in ovarian cancer." (PMID 41393507, 2025). "Suppressing HSPB1 expression also inhibits ovarian cancer cell proliferation." (PMID 41393507, 2025). "To examine whether the relationship between ZKSCAN3 and HSPB1 was also present in ovarian cancer patient samples, we analyzed the CPTAC ovarian cancer cohort, which revealed a statistically significant positive correlation between HSPB1 protein level and ZKSCAN3 protein level (p < 0.01)." (PMID 41393507, 2025). "Furthermore, we confirmed ZKSCAN3 enrichment at HSPB1 with ChIP followed by qPCR in both HEY and A2780 ovarian cancer cell lines." (PMID 41393507, 2025).
periodontitis (4 papers, 2021 to 2024). An acute or chronic inflammatory process that affects the tissues that surround and support the teeth. "The expression levels of NCOA4, SLC1A5 and HSPB1 using PCR were significantly different between normal gingival samples and periodontitis samples." (PMID 35901060, 2022). "Moreover, we found specific proteins - drivers or suppressors - associated with ferroptosis (SNCA, FTH1, HSPB1, CD44, and GCLC), revealing the co-occurrence of this specific type of regulated cell death during the clinical progression of periodontitis." (PMID 38802345, 2024). "Moreover, the expression of ferroptosis-related genes, including NCOA4, SLC1A5, HSPB1, etc. were significantly upregulated in the human periodontitis-gingival samples compared to the periodontal healthy normal gingival samples." (PMID 37710216, 2023).
pulmonary fibrosis (4 papers, 2020 to 2025). Chronic progressive interstitial lung disorder characterized by the replacement of the lung tissue by connective tissue, leading to progressive dyspnea, respiratory failure, or right heart failure. "It has been previously suggested that the HSPB1 and its phosphorylated form (p-HSPB1)-mediated IKBα-NF-κB signaling axis promotes pulmonary fibrosis progression." (PMID 39863585, 2025). "In pulmonary fibrosis, HSPB1, also known as HSP27, which has a protective role against cellular stress, has previously been reported as a regulator of fibrosis through EMT." (PMID 35130955, 2022). "In radiation-induced lung fibrosis, in which HSPB1 is overexpressed in mice, collagen deposition was induced." (PMID 35130955, 2022). "HSPB1 can inhibit the endothelial-to-mesenchymal transition (EDMT) to suppress pulmonary fibrosis and lung tumorigenesis." (PMID 32848724, 2020). "HSPB1 was found to be overexpressed in idiopathic pulmonary fibrosis (IPF) patients." (PMID 34930105, 2021). "In PF, HSPB1 regulates TGF-β-mediated lung fibroblast differentiation via the Smad3 and ERK pathways and contributes to radiation-induced lung fibrosis via the activation of the IkBα-NFκB signaling." (PMID 39863585, 2025).
status epilepticus (4 papers, 2017 to 2021). Status epilepticus is defined as a continuous seizure lasting more than 30 min, or two or more seizures without full recovery of consciousness between any of them. "Recently, we have reported that heat shock protein B1 (HSPB1) and purinergic receptor P2X7 (P2RX7) are involved in astroglial autophagy (clasmatodendrosis), following status epilepticus (SE)." (PMID 29749377, 2018).
acute kidney injury (3 papers, 2015 to 2024). Sudden and sustained deterioration of the kidney function characterized by decreased glomerular filtration rate, increased serum creatinine or oliguria. "HSPB1 enhances autophagy during acute kidney injury (AKI) and is similarly activated by misfolded proteins." (PMID 38892061, 2024).
axonal peripheral neuropathy (3 papers, 2013 to 2022). "The HSPB1 c.407G>G (p.Arg136Leu) mutation causes an adult‐onset, predominantly motor, axonal neuropathy in individuals of Jewish Iranian descent." (PMID 33973728, 2021). "Patients carrying an HSPB1 mutation are characterized by an axonal peripheral neuropathy associated with a decrease in the amplitude of the compound muscle action potentials, which is consistent with the observed decrease in the amount, density and diameter of myelinated nerve fibers." (PMID 23728742, 2013). "For example, patients carried the p.R127W of HSPB1 can manifest as axonal peripheral neuropathy, but also ALS in some." (PMID 36291591, 2022).
bladder cancer (3 papers, 2023 to 2024). "In the context of bladder cancer, circST6GALNAC6 has been shown to bind to small heat shock protein 1 (HSPB1) and block erastin-induced phosphorylation site of HSPB1, protectively in response to ferroptosis stress (Ser-15 site), thus activating the P38 MAPK pathway and facilitating cell ferroptosis." (PMID 38177102, 2024). "Binding of circST6GALNAC6 to the N-terminus of small HSPB1 was disclosed to retard the phosphorylation of Ser-15 site of HSPB1 induced by erastin, resulting in activation of p38 MAPK pathway and subsequent enhancement of cell ferroptosis in bladder cancer." (PMID 38397395, 2024).
breast tumors (3 papers, 2007 to 2022). "It has been reported a novel immune escape mechanism mediated by HSPB1, in which this protein expressed in the breast tumor microenvironment, promotes the differentiation of monocytes to macrophages with immune-tolerogenic phenotypes, which, in turn, trigger severe anergy in T-cells." (PMID 35204174, 2022). "HSPB1, a component of multiple pathways, was also down-regulated in all breast tumors." (PMID 17883861, 2007).
cataract (3 papers, 2010 to 2022). Partial or complete opacity of the crystalline lens of one or both eyes that decreases visual acuity and eventually results in blindness. "We have analyzed the cellular consequences of the stable expression of either wild type HspB5 or its cataracts and myopathies inducing R120G mutant in growing and oxidative stress treated HeLa cells that originally express only HspB1." (PMID 23950959, 2013).
coronary heart disease (3 papers, 2021 to 2024). "It has been reported that HSPB1 is not only related to iron death, but also involved in regulating cardiac immune microenvironment in coronary artery disease." (PMID 39711549, 2024). "CA9, CBS, CEBPG, HSPB1, SLC1A4, HSPB1 and TRIB3 are genes that we have screened for iron death in coronary heart disease samples." (PMID 35152560, 2022).
diabetic retinopathy (3 papers, 2012 to 2021). "HSPB1 is one of the tear proteins identified in people with diabetic retinopathy and can serve as a future early diagnostic tool for this disease." (PMID 34316222, 2021). "Using Wiki-Pi, we infer that its association to diabetic retinopathy may be mediated through its interactions with the genes HSPB1, KRAS, TMSB4X and DGKD, and that it may be involved in cellular response to external stimuli, cytoskeletal organization and regulation of molecular activity." (PMID 23209562, 2012). "Our results clearly indicate a dramatic upregulation of various crystallins in diabetic retinopathy and suggest this to be a stress response, which may be similar to the reported effects of increased levels of Hspb1 transcript in retina." (PMID 22605924, 2012).
endometrial cancer (3 papers, 2015 to 2022). Primary or metastatic malignant neoplasm involving the endometrium (mucous membrane that lines the endometrial cavity). "Transcriptome sequencing analysis showed that ANKHD1-BP3 was the mainly expressed transcript in endometrial cancer cells, and the expression of this transcript was reduced when HSPB1 was overexpressed." (PMID 36171217, 2022).
glaucoma (3 papers, 2021 to 2023). Increased pressure in the eyeball due to obstruction of the outflow of aqueous humor. "For each of the 4 clusters, notable genes associated with glaucoma, neuroinflammation, or reactive astrocytes were: Cluster 1 (Nrf2, Hspb1, S100β), Cluster 2 (Ptgs2, Clcf1), and Cluster 4 (C2, Tlr4, Lcn2, H2-T23, Thbs1, Il6ra)." (PMID 37759301, 2023). "Furthermore, exogenously applied antibodies against HspB4 and HspB5 or HspB1 to human RGC cultures at concentrations similar to those found in glaucoma patients caused apoptotic cell death." (PMID 35480891, 2022). "Moreover, HSPB1 expression increased in glaucoma patients, which involved the progressive loss of retinal ganglion cells and optic nerve degeneration." (PMID 34316222, 2021). "Immunostaining experiments have demonstrated an upregulation of HspB1 in retinal ganglion cells (RGCs), retinal vessels, and the optic nerve head of primary open-angle glaucoma (POAG) and normal-tension glaucoma patients." (PMID 35480891, 2022). "Despite showing beneficial effects in glaucoma, HspB1 has also been claimed to induce the pathogenesis of glaucoma." (PMID 35480891, 2022). "Very few glaucoma-related neuroinflammatory and reactive astrocyte genes and pathways were differentially expressed (Hsp70, Hsp90, Hspb1, C2, Tlr4, S100b, Lcn2, H2-T23), and understanding their significance to an overall neuroinflammatory astrocyte requires more focused functional testing." (PMID 37759301, 2023). "Moreover, HspB1 has been shown to promote RGC death in animal models of glaucoma." (PMID 35480891, 2022). "Studies on nonhuman primate models of glaucoma have shown elevated levels of HspB1 in RGCs and optic nerve fibers." (PMID 35480891, 2022).
hyperlipidemia (3 papers, 2022 to 2025). "In our study, we demonstrate that advanced hyperlipidemia over-regulates HSPB1, HSPB7, HSP90-α (by both mass spectrometry and immunologic assay), and HSP90-β, while HSP60’s spectral abundance was found to be down-regulated." (PMID 36232476, 2022). "To analyze whether sex, hyperlipidemia, or human HSPB1 overexpression influence the expression of genes involved in the regulation of inflammation, metabolism, and stress response, we isolated total RNA from the vWAT, and gene expression levels were measured by qPCR." (PMID 40855499, 2025). "• Overexpression of human HSPB1 failed to restore hyperlipidemia-related cardiac morphological alterations found in HFD-fed APOB-100 males, while it induced LVH in the wild-type animals of both sexes." (PMID 40855499, 2025).
liver fibrosis (3 papers, 2016 to 2025). "In liver fibrosis, HSPB1 activates JAK2/STAT3 and TGF-β1/Smad pathways, while it regulates cell proliferation and directly interacts with JAK2/STAT5 in myelofibrosis." (PMID 39863585, 2025). "In a study, notable variations in HSPB1 expression levels were observed between individuals with liver fibrosis and healthy controls, with higher HSPB1 expression showing a positive correlation with the severity of liver fibrosis." (PMID 38809509, 2024). "Hspd1 and Hspb1, two proteins uniquely identified by 2D-PAGE upon exposure of milkfish to lethal hypothermal environment, might play a critical role in decreasing intrinsic apoptotic effects and liver fibrosis." (PMID 27657931, 2016).
lung adenocarcinoma (3 papers, 2014 to 2023). A carcinoma that arises from the lung and is characterized by the presence of malignant glandular epithelial cells.
mammary adenocarcinoma (3 papers, 2012 to 2016). "Labeled primers were used to screen the 1514-1517 4bp deletion loci in Hspb1 intron 2 found in cat mammary adenocarcinoma." (PMID 28224005, 2016). "Surface bound/expressed and total Hsp25 (mouse HspB1) and Hsp72 (HspA1A) on 4T1 murine breast adenocarcinoma tumors suggest that tumor development and metastatic spread favors cells that express high levels of mouse HspB1 on their plasma surface." (PMID 22452810, 2012).
motor neuron diseases (3 papers, 2015 to 2024). "Furthermore, the protein products for several genes that have been causally linked to ALS are found within the M2 module, including HNRNPA1, MATR3, and PFN1 and TDP‐43 itself, whereas HSPB1 (in M6) has been linked to hereditary motor neuropathy, a form of motor neuron disease." (PMID 29191947, 2018). "It is possible that one or these effects, or a combination of thereof, alters the interaction of HSPB1 with proteins in the cell possibly leading to long term motor neuron diseases." (PMID 25965061, 2015). "At the same time mutations of HspB1 in the N-terminal domain that are associated with hereditary motor neuron diseases were not analyzed in detail until now." (PMID 25965061, 2015).
Oral Cancer (3 papers, 2023 to 2025). "They identified HSPB1 as a hub gene using Cytohubba and hence proposed this classifier as potentially useful in the diagnosis and development of therapeutic strategies for oral cancer." (PMID 39941210, 2025).
presbycusis (3 papers, 2014 to 2022). Bilateral hearing loss caused by progressive degeneration of cochlear structures and central auditory pathways, typically associated with the aging process. "In CBA/CaJ mice, Hspb1 [heat shock protein family B (small) member 1] shows differential expression between mild and severe presbycusis." (PMID 35463035, 2022). "An animal study reported that the heat shock protein 1 (Hspb1) gene was downregulated in middle-aged mice with mild presbycusis, whereas it was upregulated in those with severe presbycusis." (PMID 33926545, 2021). "The Hspb1 gene was found to be downregulated in middle-aged animals as well as those with mild presbycusis, whereas it was upregulated in those with severe presbycusis." (PMID 24587312, 2014).
Senile plaques (3 papers, 2019 to 2024). Senile plaques are extracellular deposits of amyloid in the gray matter of the brain. "HSPB1 is associated with senile plaques in AD and prevents the toxic effects of Aβ aggregates in vitro, and was found to be a key molecule in a regulatory network analysis integrating AD, Parkinson’s and MS." (PMID 39728495, 2024). "HspB1, HspB2, and HspB6 associate with senile plaques in AD brain tissue." (PMID 31619995, 2019). "HSPB1 can be elevated in the brain and accumulate in senile plaques in AD patients." (PMID 35099007, 2022). "In a simple case of direct interaction, sHsps would need to be located outside of cells in order to associate with and reduce toxicity of extracellular misfolded proteins, like Aβ; which has been described for HspB1, HspB5, and HspB8 in extracellular, classic, senile plaques in AD brain." (PMID 31619995, 2019).
Sepsis (3 papers, 2018 to 2023). Sepsis is defined as life-threatening organ dysfunction caused by a dysregulated host response to infection. "In summary, CD81, RPL22, GYPE, and HSPB1 were screened and they are significantly associated with the immunity in sepsis-induced ARDS." (PMID 34898369, 2022). "In contrast, HSPB1−/− mice had a significant increase in mortality, with 65% of knockout mice dying after induction of sepsis." (PMID 30131526, 2018). "Given the clinical importance of sepsis, the molecular mechanisms and tissue specific functions of HSPB1 require further investigation." (PMID 30131526, 2018). "Our results demonstrate that HSPB1 plays a critical role in protecting the host following sepsis, with markedly increased mortality in HSPB1−/− mice following CLP." (PMID 30131526, 2018). "Ten-day mortality was significantly higher in HSPB1−/− mice following the onset of sepsis (65% vs. 35%)." (PMID 30131526, 2018). "It is prompted that HSPB1 plays an important role in sepsis." (PMID 34898369, 2022). "Previous studies have revealed that HSPB1 can inhibit the occurrence of sepsis in mice." (PMID 34898369, 2022). "We therefore examined HSPB1−/− mice following CLP to test whether HSPB1 is a critical factor in limiting injury or mortality following sepsis." (PMID 30131526, 2018). "Thus while HSPB1−/− mice are uncompromised under basal conditions, HSPB1 has a critical function in vivo in sepsis, potentially mediated through alterations in arterial compliance and the immune response." (PMID 30131526, 2018). "The boxplot revealed 26 differentially expressed genes between the sepsis-induced ALI and control samples: Ncf2, Slc2a6, Cd44, Txnip, Slc2a1, Ubc, Hspb1, Zfp36, Arntl, Ddit4, Tnfaip3, Txnrd1, Mt1, Hmox1, Gch1, Gclc, Stat3, Egfr, Hif1a, Bach1, Socs1, Dusp1, Cdkn1a, Fth1, Steap3, and Alox12." (PMID 37081490, 2023).
ST Elevation Myocardial Infarction (3 papers, 2019 to 2024). A myocardial infarction that produces elevation in the ST segments of the ECG. "Another study demonstrated that HSPB1 is up-regulated and phosphorylated in the platelets of patients with ST-elevation myocardial infarction." (PMID 38429673, 2024).
amoebiasis (2 papers, 2022 to 2025). "Notably, infection-related pathways such as amoebiasis and Vibrio cholerae infection (e.g. GNAS, ACTG1 and HSPB1; adjusted P<0.01) were also identified." (PMID 40989927, 2025). "For example, among amoebiasis pathway-related proteins, integrin beta-2 (ITGB2), heat shock protein beta-1 (HSPB1), LCN2, leukocyte elastase inhibitor (SERPINB1), laminin subunit alpha-4 (LAMA4), and fibronectin (FN1) have been found to be correlated with immunity." (PMID 36387401, 2022).